NRF1 (nuclear respiratory factor 1)
Diseases named in the same sentence as NRF1 in open-access papers (continued):
Sharing a sentence is not in itself a finding about the gene and the disease.
hepatocellular carcinoma (continued). "Herein, real-time qPCR revealed that expression of Nrf1 mRNA was almost completely abolished in distinct human hepatomas, by comparison with that of their corresponding para-carcinoma tissues." (PMID 32273945, 2020). "Together, these demonstrate that knockdown of Nrf1 leads to constitutive activation of β-catenin signaling pathway, and therefore results in a significant enhancement in the in vivo malgrowth of hepatoma and its malignant metastatic potentials." (PMID 32273945, 2020). "The results unraveled that silencing of Nrf1 led to significant decreases of E-cadherin in the hepatic intratumor tissues of shNrf1-expressing hepatoma xenograft mice." (PMID 32273945, 2020). "Such silencing of Nrf1 further promoted the malgrowth of human hepatocellular carcinoma, along with malignant invasion and metastasis to the lung and liver in xenograft model mice." (PMID 32273945, 2020). "In summary, our evidence corroborates that Nrf1 functions as a dominant tumor repressor by intrinsic inhibition of the Wnt/β-catenin pathways and other signaling networks involved in human hepatoma development and progression." (PMID 32273945, 2020). "These collective results presage that migration and invasion of human hepatoma cells are promoted by knockdown of Nrf1." (PMID 32273945, 2020). "Herein, we have presented the evidence showing that silencing of Nrf1 by stable shRNA interference significantly promotes malgrowth of the human hepatocellular carcinoma, particularly its subcutaneous tumorigenesis accelerated in the xenograft model mice." (PMID 32273945, 2020). "Conversely, loss of the putative Nrf1α‘s function is proposed to be a major (or essential) contributor leading to spontaneous development of hepatoma in liver-specific Nrf1−/− mice (in which Nrf1β/γ, besides Nrf1α, is also deleted)." (PMID 27065079, 2016). "Specifically, studies using human hepatocellular carcinoma and colorectal tumor tissues show the significance of upregulated NRF-1 protein levels (mediated by neutrophil extracellular trap formation) in inducing mitochondrial biogenesis promoting tumor growth and metastasis." (PMID 39742254, 2024). "Furtherly, immunohistochemical staining manifested that protein expression of Nrf1 was substantially attenuated or almost abolished in distinct human hepatoma tissues, as coincident with pathological differentiation extents of cancer when compared to the corresponding para-carcinoma tissues." (PMID 32273945, 2020). "In addition, altered expression profiles of some Wnt/β-catenin signaling proteins were context dependent, as accompanied by the decreased expression of Nrf1 in the clinic human hepatomas with distinct differentiation." (PMID 32273945, 2020). "The cell viability was determined for whether the growth of hepatoma was affected by knockdown of Nrf1." (PMID 32273945, 2020). "In addition, altered expression profiles of some Wnt/β-catenin signaling proteins were context dependent, as accompanied by decreased abundances of Nrf1 in the clinic human hepatomas with distinct differentiation." (PMID 32273945, 2020). "Conversely, loss of Nrf1’s function by gene-targeting in mice leads to severe oxidative stress and spontaneous development of distinct pathological phenotypes, resembling human non-alcoholic steatohepatitis (NASH) with progressive hepatoma, neurodegenerative diseases or diabetes mellitus." (PMID 34268128, 2021). "In hepatocellular carcinoma ZNF281 promotes tumor progression by suppressing mitochondrial biogenesis and function via repression of key mitochondrial TFs like NRF1 and PGC-1α." (PMID 41155227, 2025). "Although the capacity of Nrf1-deficient livers to produce glucose via gluconeogenesis appeared to be unaffected 356, glucose starvation-induced rapid death of human Nrf1α, but not Nrf2-deficient hepatoma cells results from its fatal defects in the redox metabolism reprogramming." (PMID 40703332, 2025).
hepatocellular carcinoma (continued). "Interestingly, the mining of sequencing data of a cohort of patients with liver hepatocellular carcinoma (LIHC) included in The Cancer Genome Atlas (TCGA) shows that YY1, E2F4, and NRF1 expressions were significantly upregulated in the liver of HCC patients." (PMID 37627157, 2023). "Nuclear respiratory factor 1 (NRF1) is a transcription factor that participates in several kinds of tumor, but its role in hepatocellular carcinoma (HCC) remains elusive." (PMID 37875967, 2023). "As anticipated, the results revealed that migration of those shNrf1-expressing hepatoma cells, particularly derived from HepG2 and MHCC97H, was markedly enhanced by knockdown of Nrf1." (PMID 32273945, 2020). "It has been reported that the oxidants such as tertiary butyl hydroperoxide (t-BOOH), an ROS mimic, increase cellular NRF1 and TFAM gene expression in rat liver cells and hepatoma cells." (PMID 31011285, 2019). "Importantly, binding of Pal/NRF-1 to the CD47 promoter was also previously reported in human neuroblastoma and hepatoma cell lines, as well as, during arising resistance to the oncogenic B-RAF molecular inhibitors." (PMID 39742254, 2024). "Of note, all the Nrf1-silenced hepatoma xenograft mice, but not the shNC control mice, suffered from a severe syndrome resembling the human cancer cachexia." (PMID 32273945, 2020). "In support, NRF-1 regulates CD47 expression in human neuroblastoma and hepatoma cells." (PMID 29050218, 2017). "In hepatocellular carcinoma cells, PGC1α forms a complex with NRF1 and binds to the MPC1 promoter, ultimately increasing ROS formation and inducing apoptosis of HCC cells." (PMID 36902385, 2023). "Transmembrane protein 27 (CLTRN, also known as TMEM27) is a type Ia transmembrane, which can be regulated by the Nrf-1/RAN/DLD protein complex to deplete GSH and enhance the radiosensitivity of hepatocellular carcinoma (HCC) cells." (PMID 36176274, 2022). "Herein, we determined whether either Nrf1 or Nrf2 mediates a similar adaptive response to tBHQ, and thus protects human hepatocellular carcinoma cell lines (with the presence or absence of both CNC-bZIP factors) against the cytototic effects of TU." (PMID 31861550, 2019). "However, an eccentric exception is that a medium-to-low differentiated hepatocellular carcinoma (with tumour embolism being in vessels) seemed to give rise to an unexpectedly incremental expression level of Nrf1 mRNA, but not of Nrf1α proteins (d cf. #4 with #6, & S6d vs f)." (PMID 27065079, 2016).
heart failure (13 papers, 2009 to 2026). Inability of the heart to pump blood at an adequate rate to meet tissue metabolic requirements. "This research identified novel epigenetic interference of nuclear respiratory factor 1 via hypermethylation of its downstream promoter targets, further supporting a novel contribution of DNA methylation in the metabolic remodeling of heart failure." (PMID 38765775, 2024). "In this study, both in vivo and in vitro experiments proved that the key factors of PGC-1α/NRF1/TFAM signaling pathway were reduced in rats with heart failure, and QSG can upregulate the expression levels of these key factors." (PMID 35003305, 2021). "Mitochondrial biosynthesis regulated by the PGC-1α-NRF1-TFAM pathway is considered a novel potential therapeutic target to treat heart failure (HF)." (PMID 32153406, 2020). "Overall, our studies provide a basis for investigating the novel mechanisms of chagasic heart disease and designing therapies targeting restoration of NRF1/2 function in maintaining antioxidant status to prevent heart failure." (PMID 23316324, 2012). "Indeed, analysis of published datasets revealed a significant reduction of NRF1 transcript levels in heart ventricles from three independent patient cohorts with heart failure (n = 28)." (PMID 34489413, 2021). "Future studies should also determine the molecular pathway(s) by which ERα induces Pgc1α and Nrf1, and determine whether these mitochondrial changes with ERα activation in the heart are protective against heart failure." (PMID 27582063, 2016). "Although we did not determine NRF-1 levels in the heart, several studies reported NRF-1 was activated by PGC-1α to increase mitochondrial biogenesis and increased oxidative capacity in the pathologic heart such as heart failure and cardiomyopathy." (PMID 28923829, 2017). "Protein levels of PGC-1α, ERRα, Nrf1, Gabpa, and YY1 were not significantly changed in PO-induced heart failure model." (PMID 39151728, 2024).
neuroblastoma (13 papers, 2013 to 2024). Neuroblastoma (NB) is the most common solid, extracranial childhood tumor. "A ChIP-seq study using SK-N-SH human neuroblastoma cells has revealed that Nrf1 target genes contain genes associated with cell cycle regulation." (PMID 30333037, 2018). "Also in the neural context, reduced transcriptional activity of NRF1 has been associated with fragile X mental retardation syndrome and with GABA-associated neuronal disorders, and functional NRF1 has been shown to be necessary for neurite outgrowth of human neuroblastoma cells." (PMID 34359231, 2021). "Overexpression of NRF-1 increases neurite elongation in human neuroblastoma cells and mouse primary cortical neurons, but a dominant-negative mutant of NRF-1 decreases neurite elongation." (PMID 28800112, 2017). "A recent report based on ChIP Seq data from SK-N-SH human neuroblastoma cells showed that NRF1 DNA motif(s) are present in the promoters of 2470 genes." (PMID 27983596, 2016). "The nuclear respiratory factor 1 (NRF-1) is a transcription factor that was also shown to regulate Gria2 gene transcription in neuroblastoma cells." (PMID 23389038, 2013). "Observations made in human neuroblastoma cells and mouse primary cortical neurons show that transcription factor α-Pal/NRF-1 acting through CD47/IAP promoted neurite outgrowth and reduced expression of α-Pal/NRF-1 acting through CD47/IAP impaired neurite outgrowth." (PMID 37872624, 2023). "When used as a pretreatment, curcumin prevents Aβ-induced toxicity in the human SH-SY5Y neuroblastoma cell line by increasing mRNA and protein levels of mitochondrial genes, such as nuclear respiratory factor 1 (Nrf1) and mitochondrial transcription factor A (TFAM)." (PMID 33217959, 2020). "A recent study using chromatin immunoprecipitation sequencing (ChIP-seq) analysis identified 2470 potential Nrf1 targets in human neuroblastoma cells, indicating roles for Nrf1 in regulating genes for mitochondrial biogenesis and cell growth and in the pathogenesis of neurodegenerative diseases." (PMID 30333037, 2018).
Sepsis (13 papers, 2014 to 2025). Sepsis is defined as life-threatening organ dysfunction caused by a dysregulated host response to infection. "Notably, tolerance to sepsis-promoting bacteria could be affected by complementary actions of hepatocyte Nrf1 and Nrf2, as this has been strongly linked to HDL functionality and the hepatic acute phase response." (PMID 37501930, 2023). "Sepsis significantly increased the expression of Nrf1 (P < 0.001), a transcription factor involved in the regulation of key metabolic processes, including mitochondrial respiration and DNA transcription and replication." (PMID 41385533, 2025). "Studies have shown that LPS-induced sepsis results in upregulation of NRF1 and TFAM, which in turn stimulates mtDNA replication and mitochondrial biogenesis." (PMID 37101253, 2023). "During LPS-induced sepsis, the nuclear respiratory factor-1 (NRF-1), which is a transcriptional activator of mitochondrial transcription factor A (TFAM), is upregulated in hepatocytes." (PMID 31671729, 2019). "LPS has been shown to increase the expression of nuclear respiratory factor-1 (NRF-1) in hepatocytes during sepsis." (PMID 30474573, 2018). "In the present study, a more significant number of AECII apoptosis, high mitochondrial fission p-Drp1 protein levels, and low levels of mitochondrial biogenesis-related PGC1α, Tfam, and Nrf1 proteins accompanied with ATP content depression were confirmed in AECIIs in response to sepsis." (PMID 37035447, 2023). "Thus, the mitochondrial biogenesis mediators PGC-1α, mitochondrial transcription factor A (TFAM), and nuclear respiratory factor 1 (NRF-1) are upregulated in the second phase of sepsis." (PMID 33919780, 2021). "Sepsis resulted in an increase in Nrf1, Nrf2, and Sirt1 mRNA expression levels." (PMID 32545383, 2020). "However, the increases in PGC-1a and NRF-1 in the kidney were delayed in sepsis compared to the liver and heart." (PMID 24988481, 2014). "In an in vitro model of sepsis-induced hepatocyte injury, melatonin treatment increased the protein levels of PGC-1α, NRF1, and TFAM, as well as reduced MDA levels and increased SOD activity." (PMID 40429795, 2025). "Their study revealed that mitochondrial biogenesis markers, including PGC-1α, NRF1, and TFAM, and mitochondrial fusion were decreased by TRPA1 blocker treatment in kidney tissues from either healthy or sepsis mouse." (PMID 37287081, 2023). "Given that a large amount of ATP is required for kidney cortical function, Nrf-1 mRNA and NRF-1 protein was constitutively expressed before sepsis, but it also increased significantly during sepsis." (PMID 24988481, 2014). "mRNA expressions of Nuclear Respiratory Factor 1 (Nrf1), Mitochondrial transcription factor A (Tfam), and Silent mating type information regulation 2 homolog 1 (Sirt1)—regulators of biogenesis—remained unchanged between groups (SPF vs. SF and Sepsis vs. SPF)." (PMID 37106730, 2023).
liver cancer (12 papers, 2013 to 2023). An epithelial or non-epithelial malignant neoplasm that arises from the liver. "Since NRF1 was significantly associated with tumour size, we investigated whether NRF1 expression correlated with liver cancer cell growth." (PMID 35448958, 2022). "In addition, the MAPK signaling activation and aberrant cell metabolisms are also identified by transcriptomic sequencing to have been involved in Nrf1-deficient liver cancer development and malignancy." (PMID 32273945, 2020). "Taken altogether, these results imply that distinct extents of Nrf1 deficiency might contribute to differential expression profiles of the Wnt/β-catenin signaling responsive genes, which could be involved context-dependently in the human liver cancer development and progression." (PMID 32273945, 2020). "Together, it is inferable that Nrf1 is endowed with its intrinsic function as a tumor suppressor in defending liver cancer development." (PMID 32273945, 2020). "In the present study, we have corroborated the axiomatic rationale that Nrf1 is endowed with a dominant tumor-preventing function against human liver cancer development and malignant progression." (PMID 32273945, 2020). "Overall, unraveling the unique function of Nrf1, which is distinctive from Nrf2, in liver cancer malignancies is likely to lead to novel preventive and therapeutic strategies to be paved against human cancer." (PMID 32273945, 2020). "Another mouse model showed that knocking out nuclear respiratory factor-1 (Nrf1), an essential transcription for mediating oxidative stress, induces steatosis, fibrosis and liver cancer, eventually." (PMID 30761356, 2018). "In this study, we aimed to investigate whether NRF1 can affect liver cancer cell growth." (PMID 35448958, 2022). "Remarkably, a similar enrichment for YY1, NRF1, E2F4, and FOXP3 TFs was also identified by GO-Elite in both the livers of miR-122 KO animals (GSE31453) and in the mouse model for liver cancer (GSE27713)." (PMID 37627157, 2023). "Of interest is the recent finding of a role for the transcription factor Nrf-1, a central player in controlling expression of antioxidant genes through binding to ARE sequences, in NASH and hepatic cancer development." (PMID 23967134, 2013). "After liver-specific deletion of NRF1, mice could develop all NAFLD features including steatosis, fibrosis, cirrhosis, and liver cancer." (PMID 33868403, 2021). "Likewise, liver-specific inactivation of the Nrf1 gene in adult mice has been reported to trigger NASH, suggesting that the proper activity of NRF1 and NRF3 blocks carcinogenesis, including liver cancer." (PMID 32751080, 2020). "Thereby, Nrf1 is considered to mediate the basic cytoprotective response against oxidative stress in the pathogenesis of chronic liver diseases, e.g., nonalcoholic steatohepatitis (NASH) and its malignant transformation to liver cancer." (PMID 31861550, 2019). "Interestingly, both Nrf-1 and APE1 are over-expressed in liver cancer." (PMID 23967134, 2013). "Other non-neuronal roles attributed to NRF1 are the regulation of oncogenesis, stem cell aging, telomere transcription and oxidative stress protection and lipid homeostasis in the liver; liver-specific Nrf1 conditional knockout mice develop steatohepatitis and spontaneous liver cancer." (PMID 34359231, 2021).
type 2 diabetes (12 papers, 2010 to 2026). "This notion is also reinforced by further investigation of other organ-specific Nrf1 deficiency or its over-activation in mice, which exhibit distinct pathological phenotypes, such as type 2 diabetes, neurodegenerative and cardiovascular disease." (PMID 30562963, 2018). "Moreover, several independent lines of evidence indicated that NRF1 is implicated in lipid droplet accumulation, cell proliferation and apoptosis of the mouse preadipocyte cell line 3T3-L1 and the pathogenesis of type 2 diabetes." (PMID 30618832, 2018). "Additionally, decreased concentrations of glucose transporter 4 (GLUT4) as a result of reduced NRF-1 expression in sedentary animals leads to a fall in glucose transport which predisposes individuals to type 2 diabetes." (PMID 20885954, 2010). "The pathophysiological phenotype results from deficiency of almost all Nrf1 isoforms in mouse islets and MIN6 β-cells, leading to a marked increase in basal insulin release with reduced GSIS; this was viewed as a β-cell phenotype reminiscent of the early stage of type-2 diabetes." (PMID 40703332, 2025). "As an established regulator of mitochondrial biogenesis, NRF1 has been attributed an essential role in the cardioprotective effects of circulating adiponectin via AMPK-PGC-1α-NRF1 metabolic axis, a molecular cascade that may be dysregulated in hearts of murine models of type 2 diabetes." (PMID 31920982, 2019). "Our results demonstrated for the first time that Pg, a classical thiazolidinedione drug for type 2 diabetes treatments, can be used to efficiently promote mitochondrial biogenesis of hMSC by activating the PGC-1α/NRF1/TFAM pathway." (PMID 37723135, 2023). "The ever-accumulating evidence has demonstrated that Nrf1 is a key player in the pathogenesis of NASH and HCC, as well as other relevant neurodegenerative diseases and type 2 diabetes." (PMID 30562963, 2018).